GLI3 (GLI family zinc finger 3)
Diseases named in the same sentence as GLI3 in open-access papers (continued):
Sharing a sentence is not in itself a finding about the gene and the disease.
Pallister-Hall syndrome (continued). "Moreover, several genes that are transactivated by this complex are associated with other, related syndromes, such as Jagged1 (JAG1; Alagille syndrome), MYC proto-oncogene N (MYCN; Feingold syndrome) and glioma-associated oncogene family zinc finger 3 (GLI3; Pallister-Hall syndrome)." (PMID 36361852, 2022). "Mutations in GLI3 cause several congenital conditions, including Pallister-Hall syndrome (PHS), which is characterized by polydactyly and hypothalamic hamartoma." (PMID 34631784, 2021). "A specific example is Pallister-Hall syndrome (MIM #146510) where genetic alterations of GLI3, a transcriptional effector in the SHH signaling pathway, lead to developmental defects of multiple organ systems including uni- and bilateral CAKUT." (PMID 38213489, 2024). "GLI3 is known to play a role in development-associated diseases such as Greig cephalopolysyndactyly (GCPS) and Pallister-Hall Syndrome (PHS)." (PMID 35937499, 2022). "It shows an autosomal dominant inheritance pattern, and Gli3 has been recognized as the causative gene for GCPS and its related disorder, Pallister-Hall syndrome." (PMID 31781166, 2019). "For example, Pallister-Hall Syndrome (PHS) results from a C-terminal truncation of Gli3 protein that renders it a constitutive repressor." (PMID 21209912, 2010). "When comparing HLS with other fetal malformation syndromes, Pallister-Hall syndrome (PHS, MIM 146510) that is caused by mutations in the GLI3 gene, probably has the most resemblance to HLS." (PMID 19400947, 2009). "Mutations that are predicted to generate a truncated protein similar in size to GLI3 repressor are observed in humans with Pallister-Hall Syndrome (PHS) and renal dysplasia." (PMID 19809516, 2009). "Human variants in the GLI3 gene are known to cause Pallister-Hall Syndrome (PHS; OMIM: 146510) and Greig cephalopolysyndactyly syndrome (GCPS; OMIM: 175700), and non-syndromic postaxial polydactyly types A1 and B (PAPA1/PAPB; OMIM: 174200) and preaxial polydactyly type IV (PPD-IV; OMIM: 174700)." (PMID 37675356, 2023). "Pallister-Hall syndrome (OMIM #146510, PHS) is a rare autosomal dominant condition (prevalence unknown) caused by a heterozygous mutation in the GLI3 gene, a zinc finger transcription factor gene located on chromosome 7p14.1." (PMID 35331151, 2022). "Interestingly, the difference between Pallister-Hall syndrome and GLI3-mediated polydactyly syndromes has also been attributed to the GLI3R overexpression." (PMID 32591344, 2021). "The presence of renal agenesis/dysplasia in humans with Pallister-Hall syndrome and GLI3 repressor dominant murine models suggests that a fine spatial and lineage-specific balance of GLI activator and GLI repressor must be maintained for normal renal morphogenesis." (PMID 19809516, 2009). "The pathogenic variants of GLI3 gene cause various malformations including Greig cephalopolysyndactyly (GCPS) syndrome and Pallister-Hall syndrome (PHS) in an autosomal dominant pattern." (PMID 29368652, 2018). "Among other genetic syndromes, mutations in GLI3 are found in patients with Greig-cephalopolysyndactyly-syndrome (GCPS [MIM175700]), Pallister-Hall syndrome (PHS [MIM146510]) and - in one patient - acrocallosal syndrome [MIM200990]." (PMID 19829694, 2009).
breast carcinoma (15 papers, 2009 to 2025). "In summary, we found that loss of MED12 promotes GLI3-dependent SHH signaling in breast cancer cells which subsequently leads to enhanced cell proliferation and colony formation ability." (PMID 38915457, 2024). "Parathyroid hormone-related protein (PTHrP), NRG3, and GLI3 are additionally recognized as having a role in breast cancer pathogenesis and prognosis." (PMID 40001874, 2025). "Overall, our results show that solasonine and AB23A are promising targeted therapies for breast cancer cells with dysregulated GLI3-dependent SHH signaling such as is seen in MED12-altered cells." (PMID 38915457, 2024). "Our results show that loss of MED12 leads to enhanced cellular proliferation and colony formation of breast cancer cells through a mechanism that involves activation of GLI3-dependent SHH signaling, a pathway that is central to breast development and homeostasis." (PMID 38915457, 2024). "Furthermore, we successfully found two natural compounds that can potentially combat MED12-altered breast cancer by targeting the GLI3-dependent SHH signaling pathway." (PMID 38915457, 2024). "It has already been reported a clear role for GLI3 transcription factors in the normal mouse mammary gland development and GLI3 may have a particular role in the breast cancer metastasis to bone in vivo as GL3 is involved in mediating epithelial-stromal tissue interaction." (PMID 19828084, 2009). "GLI3 in particular is required for the formation of mammary placodes in utero, and its knockdown in invasive MDA-MB-231 human breast cancer cells has previously been shown to inhibit tumor proliferation, migration, and invasion." (PMID 40001874, 2025). "GLI3 and PICK1 were found to over-express in various cancers, including colorectal cancer, ovarian cancer, breast cancer, prostate cancer, and oral squamous cell carcinoma." (PMID 38280969, 2024). "Overall, these results suggest that solasonine and AB23A inhibit GLI3-mediated SHH signaling and are therefore promising therapeutic agents for MED12 downregulated breast cancer." (PMID 38915457, 2024). "Since prior results have shown a link between loss of MED12 and hyperactivation of GLI3-mediated SHH signaling in prostate cancer and X-linked intellectual disability syndromes, we performed quantitative PCR to determine whether dysregulated signaling also occurs in breast cancer cells." (PMID 38915457, 2024). "The positive correlation of Gli3 with tumor progression has been observed in HCC, pancreatic cancer, colon cancer, ovarian cancer, breast cancer, and bladder cancer." (PMID 36959801, 2023). "In silico analyses of gene expression profile datasets identified GLI3 as a putative interacting partner of TBX3, an important regulator in embryonic mammary gland development commonly overexpressed in breast cancer (see also section on TBX below)." (PMID 35846378, 2022). "Similarly, although Gli3 does not have a direct role in breast cancer, it has been found to cooperate with other genes such as androgen receptor (AR), estrogen receptor (ER) and Eph10A to promote tumorigenesis and invasive phenotypes." (PMID 35846378, 2022). "In addition, the absence of SMO expression was confirmed in seven cell lines, including five breast cancer cell lines and the stomach cancer AGS cell line, whereas the lack of SMO was accompanied by undetectable GLI3 in colon cancer HT29 cells." (PMID 32784501, 2020).
polydactyly (15 papers, 2010 to 2025). A disease characterized by the presence of polydactyly, including syndromic and non-syndromic forms. "Seven novel GLI3 variants and three previously reported GLI3 variants were identified in ten Chinese families with polydactyly." (PMID 41142227, 2025). "GLI family zinc finger 3 (GLI3) is a classical causative gene of polydactyly, and serves as a pivotal transcription factor in the hedgehog signaling pathway, regulating the development of the anterior-posterior axis in limbs." (PMID 39080720, 2024). "To investigate the genotype-phenotype correlation further, we analyzed 246 cases of polydactyly linked to GLI3 variants." (PMID 39080720, 2024). "One study identified three cases of GLI3 variants (c.1320_1321insT, c.2372delC, and c.2374C>T) in patients with isolated polydactyly that were subject to nonsense-mediated mRNA decay (NMD)." (PMID 37675356, 2023). "In keeping with this notion, we also identified and functionally validated a novel GLI3 loss-of-function mutation in a KS patient who also exhibited polydactyly, a well recognized phenotypic feature of GLI3-related human diseases." (PMID 31767679, 2020). "Pathogenic mutations in the GLI3 gene (glioma‐associated oncogene family zinc finger 3) have been associated with both nonsyndromic and syndromic polydactyly." (PMID 31115189, 2019). "Our study also demonstrated the important role of GLI3 in causing nonsyndromic postaxial polydactyly." (PMID 31115189, 2019). "As there is a broad spectrum of polydactyly types caused due to pathogenic sequence variants in the coding sequence of the GLI3 gene or within the 800 bp ZRS region, thus genetic heterogeneity is expected across different ethnic groups and populations." (PMID 30459804, 2018). "Notably, GLI1 and GLI3 are crucial for limb development, with GLI3 being a classical gene implicated in polydactyly." (PMID 39080720, 2024). "Furthermore, GLI3 mutations in humans have been reported in nonsyndromic forms of polydactyly and syndromic forms of polydactyly of which a subset of patients display neonatal hypogonadism (micropenis and undescended testes)." (PMID 31767679, 2020). "Mutations in the limb development related gene GLI3 have been associated with polydactyly." (PMID 27386344, 2016). "Various exome sequencing and targeted gene studies have implicated several genes in congenital limb defects, including polydactyly (e.g., GLI3, TWIST1, HOXD13, etc.), syndactyly (FGFR2, GLI3, HOXD13, GJA1, etc.), and ectrodactyly, e.g., TP6315,24." (PMID 41510282, 2025). "We identified three pathogenic GLI3 variants in polydactyly patients, broadening the genetic spectrum of GLI3 and contributing significantly to genetic counseling and diagnosis for polydactyly." (PMID 39080720, 2024). "In conclusion, there are two distinct phenotypes within the GLI3-mediated polydactyly population: patients with more posteriorly and more anteriorly oriented hand anomalies." (PMID 32591344, 2021). "The current genetic and molecular classification suggest that at least six different types of polydactylies are caused by mutations in two different genes, i.e., SHH enhancer ZRS and the GLI3, causing PPD1, PPD2, TPT-PS, PPD4, PAPA1, and Haas type." (PMID 30459804, 2018). "Yet, the exact genotype and phenotype correlation with Gli3 mutations have not been developed due to the complex interaction of several other genes in the pathogenesis of polydactyly and bifunctional transcriptional switch." (PMID 30459804, 2018). "Indeed, GLI3 variants found in GCPS or isolated polydactylies, which have no renal manifestations, are proposed to cause functional haploinsufficiency of the GLI3 protein." (PMID 37675356, 2023). "The GLI3 mutation causing isolated polydactyly is not restricted to one specific domain." (PMID 31115189, 2019).
acrocallosal syndrome (13 papers, 2008 to 2024). Acrocallosal syndrome (ACS) is a polymalformative syndrome characterized by agenesis of corpus callosum (CC), distal anomalies of limbs, minor craniofacial anomalies and intellectual deficit. "Recently, mutations in the Kif7 gene involved in ciliogenesis and GLI3 processing have been found in human patients suffering from acrocallosal syndrome, characterized by Corpus Callosum and digit malformations." (PMID 22479201, 2012). "Acrocallosal syndrome featured with cerebellar hypoplasia is associated with GLI3 mutation." (PMID 38409116, 2024). "Interestingly, our work brings a mechanistic interpretation to the observation that Gli3 mutations have been found in human patients suffering from Acrocallosal syndrome." (PMID 22479201, 2012). "Furthermore, we show that missense mutations in this region, as observed in GCPS and acrocallosal syndrome patients, lead to changes in the subcellular localization of the GLI3 protein and interfere with its regulation by the MID1-α4-PP2A complex." (PMID 19829694, 2009). "Moreover, prolonged proliferation of cortical progenitor cells could not only underlie the macrocephaly in acrocallosal syndrome patients who carry mutations in GLI3, but also the agenesis of the corpus callosum in these patients." (PMID 30093555, 2018). "Interestingly, some GCPS point mutations and a mutation in a patient with acrocallosal syndrome are located in the identified MID1-α4-PP2A complex-dependent regulation domain of GLI3 [A943P (as found in one patient with acrocallosal syndrome), I808M and P707S (as found in GCPS patients)]." (PMID 19829694, 2009). "GLI3 mutations are associated with several human syndromic [GCPS, PHS, acrocallosal syndrome] and non-syndromic (isolated) congenital limb malformations [PPD-IV, PAPA/B]." (PMID 22903559, 2012). "Mutations in the transcription factor GLI3 have been associated with several phenotypes, including GCPS, PHS and - in one patient - acrocallosal syndrome." (PMID 19829694, 2009). "First, there is a single case of a patient with a phenotype indistinguishable from acrocallosal syndrome who has a p.A934P GLI3 mutation." (PMID 18435847, 2008). "Interestingly, the three GLI3-related conditions GCPS, PHS and acrocallosal syndrome show phenotypic overlap with Opitz BBB/G syndrome (OS [MIM300000 and 145410]), a midline malformation syndrome caused by loss-of-function mutations of MID1." (PMID 19829694, 2009). "Although the gene for acrocallosal syndrome has not been determined, testing for a large deletion of the GLI3 locus can be critical to make this distinction." (PMID 18435847, 2008).
colon carcinoma (13 papers, 2013 to 2024). "A novel variation in HH signaling that sustains the colon tumor microenvironment inhibits the repressor form of GLI3 called GLI3R." (PMID 33494284, 2021). "In this study, SMO and GLI3 were undetectable in the HT29 colon cancer cell line." (PMID 32784501, 2020). "Moreover, in murine embryonic fibroblasts and human colon carcinoma cells GSK-3β dependent phosphorylation of GLI3 leads to processing into its transcriptional repressor form GLI3R." (PMID 28575066, 2017). "Finally, we detected significant changes in GLI-3 expression in colon cancer cells, a described target gene transcription repressor of Hedgehog signaling pathway." (PMID 24946763, 2014). "Furthermore, treating colon cancer cells (both cell lines and ex vivo specimens) with GSK3β inhibitor lithium chloride (LiCl) enhances its phosphorylation on S9 and promotes the formation of Gli3/SuFu/GSK3β complex, with consequent phosphorylation and inactivation of Gli3." (PMID 32767962, 2021). "Together with the role of functional SMO in regulating GLI3 activity, it suggests an SMO-dependent GLI signaling in colon cancer tumorigenesis." (PMID 34572373, 2021). "The treatment with Bozepinib induced a strong expression of GLI-3 protein level in both ALDH+ and ALDH- colon cancer cells." (PMID 24946763, 2014). "GLI3 activation/overexpression has been shown to promote tumor progression in colon cancer but not in other models such as gallbladder or cervical cancer thus supporting tumor type-specific activities." (PMID 37208504, 2023). "High levels of GSK3β found in colon cancer tissues up-regulate non-canonical HH signaling through maintaining the activator form of GLI3, thus effectively promoting cancer cell survival." (PMID 33494284, 2021). "Suppression of GLI1/GLI2 functions by a C-terminus truncated GLI3 repressor mutant (GLI3R), or by GANT61, a pharmacological inhibitor of GLI1/GLI2, reduced hTERT protein expression in human colon cancer, prostate cancer and Glioblastoma multiforme (GBM) cell lines." (PMID 24086482, 2013).
colorectal cancer (12 papers, 2017 to 2025). A primary or metastatic malignant neoplasm that affects the colon or rectum. "The odd ratio for cancer relapse in high GLI1/GLI3 expression is 1.69, indicating that high expression of GLI1/GLI3 signaling molecules increases the risk of cancer relapse by 69% in colorectal cancer patients after chemotherapy." (PMID 28413604, 2017). "Later, genetic studies have permitted the identification of new mutations in the GLI1 and GLI3 genes, probably associated with gains of function in breast and pancreatic cancer, as well as polymorphisms in GLI3 that may predispose to colorectal cancer." (PMID 36765685, 2023). "In colorectal cancer, Gli3 knockdown reduces cell migration and invasion by affecting epithelial-mesenchymal transition through the ERK signaling pathway." (PMID 41018112, 2025). "In pancreatic cancer, Gli3 mediates cell survival and increased cell resistance to cyclopamine, while in colorectal cancer, Gli3 augments tumorigenicity by up-regulating adherence-related genes 69,70." (PMID 35069908, 2022). "In two independent studies, a positive correlation between Shh and GLI3 has also been reported in colorectal cancer tissues from patients." (PMID 34572373, 2021). "For instance, functional SMO is required for the expression of GLI3 in colorectal carcinoma cell lines, and promoter methylation of SMO led to decreased GLI3 expression." (PMID 34572373, 2021). "Elevated Gli3 expression correlated with poor prognosis in patients with colorectal cancer." (PMID 41018112, 2025). "Furthermore, the GLI3-mediated tumorigenesis in several colorectal cancer cell lines, such as LOVO, HT29, and SW480 cells, were found to be dependent on active SMO and Shh signals." (PMID 34572373, 2021). "However, we found GLI2 and GLI3 were barely detectable in colorectal cancer cells." (PMID 35359953, 2022). "Conversely, treating colorectal cancer cells with demethylating agents 5-aza-20—deoxycytidine (5aza-dC) and TSA restored both SMO and GLI3 expression." (PMID 34572373, 2021). "PGE2 treatment of colorectal cancer cells increased the abundance of Gli1 and Gli2 proteins, reaching maximum at approximately 1 h, with no appreciable effect on the expression of Gli3 protein." (PMID 34267186, 2021). "In another study, GLI3-FL (but not GLI3-R) induced more anchor-independent growth in the human colorectal cancer cell lines HCT116, HT29, SW480 and DLD-1 which was also visible upon SHH stimulation suggesting GLI3 regulation of colony formation occurs in a paracrine manner as well." (PMID 32245491, 2020).
cervical carcinoma (9 papers, 2009 to 2024). A carcinoma arising from either the exocervical squamous epithelium or the endocervical glandular epithelium. "Hh signaling is involved in the development of cervical cancer; the expression of all signaling molecules of this pathway (Shh, PTCH, Smo, Gli-1, Gli-2, and Gli-3) is increased in cervical carcinoma and is very rarely found in normal cervical epithelium." (PMID 39274874, 2024). "GLI3 affects proliferation and apoptosis in cervical cancer cells and was targeted by miRNA-218 and miRNA-506." (PMID 33506047, 2021). "GLI3 was significantly upregulated in solid cancer types including pancreatic cancer, cervical cancer, and oral squamous cancer." (PMID 33506047, 2021). "Semi-quantitative analysis of GLI1, GLI2 and GLI3 in cervical cancer cells demonstrated elevated levels of GLI1 transcripts particularly in HPV16-positive SiHa cells." (PMID 27678330, 2016). "Further studies showed that miR-506 can inhibit cervical cancer growth by directly targeting the hedgehog pathway transcription factor Gli3." (PMID 26452129, 2015). "Endogenous GLI3 is expressed in all these cell lines including HeLa (cervix carcinoma) and U373MG (glioblastoma)." (PMID 19829694, 2009). "In addition, GLI3 affects proliferation and apoptosis in cervical cancer cells and was targeted by miRNA-218 and miRNA-506." (PMID 33506047, 2021). "As example, miR-133b has been shown to stimulate the tumorgenesis and metastasis of human cervical carcinoma, and thus gene targeting for miR-133b and its target GLI3 might be used to treat cervical carcinoma and other tumors in the future." (PMID 26755652, 2016).